CD47 (CD47 molecule)
Diseases named in the same sentence as CD47 in open-access papers (continued):
Sharing a sentence is not in itself a finding about the gene and the disease.
tumor (continued). "Furthermore, the concomitant blockade of the CD47/SIRPα axis with tumor-targeting monoclonal antibodies such as trastuzumab may provide a synergistic phagocytic antitumor activity." (PMID 38433837, 2024). "Since CD47 can competitively occupy SIRPα, the overexpression of CD47 on T-EVs may disrupt CD47/SIRPα signal and lead to enhanced macrophage-mediated phagocytosis of tumor cells." (PMID 37283792, 2023). "Taken together, these independent studies indicate that CD47 blockade suppresses lung tumor growth by inducing phagocytic clearance of cancer cells by DCs and macrophages, which can engage adaptive immune responses to further inhibit tumor progression in immunocompetent hosts." (PMID 37958404, 2023). "Antisense knockdown of CD47 can delay the growth of some cancers in immune-competent mice, but tumor ablation and increased long-term survival have been achieved only by combining with local tumor irradiation, cytotoxic chemotherapy, or anti-CTLA4 or anti-PD-1 ICI." (PMID 36768931, 2023). "Given that overexpression of CD47 by tumor cells to circumvent phagocytosis of macrophages is one of the means to induce immune escape 11, we analyzed whether anti-CD47 scFv secretion made a difference to phagocytic efficiency of macrophages against tumor cells." (PMID 37781520, 2023). "CD47 is a transmembrane protein that acts as a ligand for signal regulatory protein-α (SIRPα), which is expressed on macrophages, and this interaction inhibits the phagocytic property of macrophages, which leads to increased tumor growth via less antigen presentation." (PMID 36769180, 2023). "Indeed, the administration of an anti-CD47 mAb was able to significantly improve the uptake of tumor-derived DNA by DCs, thus determining the activation of the cGAS/STING pathway and, as a consequence, the infiltration and activation of NK cells via CXCL9 and IL-12." (PMID 37298470, 2023). "Moreover, The TSP-1/CD47 expression and interaction increase under hypoxia to promote tumor growth." (PMID 36882399, 2023). "For example, the combination of the CD47 blocking antibody magrolimab with rituximab demonstrated clinical activity in patients with non-Hodgkin’s lymphomas and was the first clinical study to confirm the scientific rationale for myeloid immune checkpoint blockade in tumor patients." (PMID 37346044, 2023). "The CD47 enabled cancer cells to escape innate and adaptive immune surveillance leading to metastatic spread, which could be restricted by the administration of anti-CD47 antibodies through affecting tumor growth and tumor microenvironment signaling." (PMID 38111586, 2023). "In addition, CD47 on tumor cell membrane can inhibit the phagocytosis of DC to tumor cells." (PMID 37153795, 2023). "Moreover, the choice of tumor model used in preclinical research may influence the overall response to anti-CD47 therapy, emphasizing the importance of considering tumor heterogeneity and complexity in therapeutic development." (PMID 38125492, 2023). "In addition, with anti-CD47 therapy, tumor cells may be eliminated through natural-killer-cell-mediated antibody-dependent cytotoxicity, as well as complement-dependent cytotoxicity." (PMID 37373873, 2023). "In addition to the surface of tumour cells, CD47 is widely expressed on immune cells." (PMID 38037074, 2023). "For instance, CD40 could enhance the phagocytic activity of macrophages recovered by CD47‐SIRPα blockade, and a fusion protein with high affinity to bind CD40 and CD47 performed better than either CD47 blockade or CD40 agonist alone in a mouse CT26 tumor model." (PMID 37706196, 2023). "Therefore, CD47 expression on stromal cells significantly impacts tumor growth and progression." (PMID 38188674, 2023). "Thus, CD47 inhibition and Fc-mediated immune effector functions may contribute to the anti-tumor efficacy of IgG1-based anti-CD47 antibodies." (PMID 37958404, 2023). "Therefore, inhibiting CD47/SIRPα axis has a significant impact on tumor immunotherapy." (PMID 36726125, 2023).
tumor (continued). "However, the combination of neuraminidase treatment and CD47 blockade may be required for enhancing IgA-mediated killing of resistant tumor cells with high CD47 expression." (PMID 37444515, 2023). "Thirdly, in the development of anti-CD47 bsAbs, another challenge arises from the widespread expression of CD47 on normal tissues, leading to an "antigen sink" effect that hinders the effective binding of therapeutic antibodies with targeted tumor cells in vivo." (PMID 38125492, 2023). "In addition, the CAR T cells also acts as a medium to achieve local delivery of anti-CD47 antibodies, reduce the impact on normal cells, and block the anti-phagocytosis effect of tumor cells, thus ameliorating the immunosuppressive TME, diminishing tumor immune evasion." (PMID 37781520, 2023). "However, whether or how oncogenic activation of receptor tyrosine kinases, which are crucial drivers in tumor development, regulates CD47 expression is unknown." (PMID 37541303, 2023). "Furthermore, these inhibitory mechanisms may impede phagocytosis in wild type phagocytes that express SIRPα and CD47 of any cellular target on which CD47 is expressed (e.g., red blood cells, platelets and tumor cells)." (PMID 37872624, 2023). "In addition, CD47 has been found to be involved in a complex interplay with microglia and other types of cells, and increasing evidence indicates that CD47 can be targeted as part of immune modulatory strategies for non-neoplastic diseases as well." (PMID 38125492, 2023). "In addition, researchers developed plasmid CAR (pCAR) containing nano porters (NP), which target TAMs and generate CAR-Ms in-vivo and demonstrated that the combination of NP-pCAR and anti-CD47 showed the most potent anti-tumor capacity compared to NP-pCAR or anti-CD47 alone." (PMID 38017494, 2023). "Drugs targeting MHCI/LILRB1 axis may promote anti-tumor immune response and play a synergistic role with drugs targeting CD47-SIRPA axis; CD24-SIGLEC10 interaction blocks the cytoskeleton rearrangement required by macrophage phagocytosis and triggers the inhibitory signal transduction cascade." (PMID 37138287, 2023). "However, in the context of tumor cells, the overexpression of "Don't eat me" signals like CD47, PD-L1, and beta-2 microglobulin (B2M), an anti-phagocytic subunit of the primary histocompatibility complex class I, enables these cells to evade macrophages and proliferate uncontrollably." (PMID 37822610, 2023). "Thus, CD47 has emerged as a promising checkpoint molecule for anti-tumor therapy." (PMID 37241964, 2023). "Therefore, blockade of CD47/SIRPα may not only reprogram macrophages polarization, but also enhance the anti-tumor activity of NK cells." (PMID 36845095, 2023). "It has been shown that CD47, which is highly expressed on cancer cells, and regulatory protein α (SIRPα), a macrophage expressing receptor, form checkpoints for innate immunity, inhibiting macrophage-mediated phagocytosis and leading to immune escape of tumor cells." (PMID 37259426, 2023). "Besides, the interaction between TSP-1 with CD47 directly inhibits tumor adaptive immunity." (PMID 36959862, 2023). "Therefore, targeting Siglec-9 may only be beneficial in certain tumor types, whereas targeting CD47 can have broad applicability across a wide range of both solid and hematological malignancies." (PMID 37444515, 2023). "Notably, CD47 IgG4 antibodies may exert dual function by blocking CD47 at the tumor cell site and engaging activating FcγR at the effector cell side to provide an ‘Eat Me!’ signal." (PMID 37781391, 2023). "Thus, THBS2 might promote cancer progression by remodeling the TME, affecting CD47-mediated signaling pathways, activating the pro-tumor functions of ADAMTSs, and enhancing MMP-2 expression." (PMID 35701829, 2022).
tumor (continued). "CD47-mediated immune evasion relies on its different cellular functions; however, many studies have mostly focused on its interaction with the signal-regulatory protein alpha (SIRPα), whose downstream effect of phosphorylation is the inhibition of tumor cell phagocytosis." (PMID 35054787, 2022). "Besides the innate immune system, the adaptive immune system may also contribute to the tumor growth inhibition on the SIRPα-CD47 pathway blockade." (PMID 35256517, 2022). "Furthermore, blockade of CD47 induced by bevacizumab therapy inhibited tumour metastasis." (PMID 35694254, 2022). "Moreover, neutrophils may also prominently contribute to the enhanced tumor elimination after CD47-SIRPα disruption." (PMID 35884427, 2022). "Therefore, blocking the interaction between CD47 and SIRPα can enhance tumor therapeutic efficacy." (PMID 36733388, 2022). "However, CD47 blockade may also contribute to tumor elimination through promoting cytotoxic T cell responses." (PMID 35538512, 2022). "In addition, CD47 on EVs and CD47 cross-dressed on tumor cells may also neutralize CD47 ligands, such as TSP-1 that has been shown to induce CD47 activation leading to apoptosis in tumor and endothelial cells, hence, favoring tumor growth." (PMID 36454036, 2022). "In addition to downregulation of CD47 on tumor cells, it was shown that the treatment of neutrophils with Gal-9 induced neutrophil activation, such as induced calcium flux, and degranulation, measured by upregulation of CD11b, CD18, CD11c, CD15, CD66b and CD63 on the cell’s surface." (PMID 35884427, 2022). "And the study found that at the boundary between tumor and peripheral tissue, the bidirectional interaction of ligand-receptor help to maintain the intratumoral structure and the spatial distribution of PROM1+ and CD47+ CSCs; this process is associated with TME remodeling and tumor metastasis." (PMID 36303541, 2022). "Cisplatin, but not ifosfamide or methotrexate, could also increase the content of IL-18 in macrophage-conditioned media and tumors, and the effects of these drugs on CD47 upregulation in tumor cells observed in vitro and in vivo were correlated with IL-18 levels induced by them." (PMID 36274066, 2022). "In addition, therapies that block the CD47/SIRPα axis may stimulate phagocytosis of cancer cells in vitro and anti-tumor immune responses in vivo through macrophages and other immune cells." (PMID 35701829, 2022). "Moreover, in other cancer types, anti-CD47 blockade has been demonstrated to enhance macrophage ADCP of tumour cells in response to TAA-targeting IgG mAbs, including Trastuzumab, anti-CD20 IgG1 Rituximab (Rituxan), and anti-epidermal growth factor receptor (EGFR) IgG1 Cetuximab (Erbitux)." (PMID 35020853, 2022). "However, even under these circumstances, phagocytosis might decrease at later stages of tumor growth due to increased expression of “don't eat me” signals such as CD47 by tumor cells." (PMID 35194846, 2022). "Whereas CD47-SIRPα targeting is often referred to as a method to improve macrophage mediated-phagocytosis, it is clear that neutrophils may also play a critical role as effector cells towards cancer cells during tumor-targeting antibody therapy in general." (PMID 35884427, 2022). "Phagocytic checkpoint blockade, including anti-CD47 therapy and PD-L1 blockade, stimulates the innate and adaptive immune systems to generate anti-tumor responses, combining them with existing cancer immunotherapy strategies to improve the response rate to tumor treatment." (PMID 36258231, 2022). "Indeed, the CD47 expression level was increased in tumor tissues with CaCE treatment." (PMID 36054073, 2022). "Therefore, targeting the innate immune checkpoint CD47-SIRPα could be a potential way to improve current antibody therapies, as it can stimulate neutrophil-mediated tumor killing." (PMID 35884427, 2022).
tumor (continued). "Furthermore, knocking down of IL18R1 in HOS and SJSA-1 cells showed similar effects with IL-18BP treatment on suppressing CD47 expression, enhancing macrophage infiltration and activation and inhibiting tumor growth." (PMID 36274066, 2022). "Together, our results highlight the need to integrate PMNs in the development of molecules targeting the CD47-SIRPα immune checkpoint and to design agents able to enhance myeloid cell function while limiting adverse effects on healthy cells able to participate in the anti-tumor immune response." (PMID 35795660, 2022). "In addition to CD47, the MHC I component β2-microglobulin and CD24 have also been shown to act as potent “do not eat me” signals, upon binding to their respective inhibitory receptors LILRB1 and Siglec-10 on tumor-associated macrophages (TAMs)." (PMID 35269922, 2022). "Thus, blocking the interaction between CD47 and SIRPα may enhance anti-tumor effects by neutrophils in the presence of tumor-targeting monoclonal antibodies." (PMID 35884427, 2022). "Therefore, blocking the CD47/SIRPα cross talk may be a promising approach for cancer immunotherapy either on its own or via integration with other tumor-targeted therapies, as reported in numerous preclinical studies." (PMID 35978372, 2022). "Finally, pharmacologic or genetic CD47 inhibition in subcutaneous mouse tumors growing in immunocompetent mice still led to enhanced tumor inhibition following irradiation, indicating that the antitumor effects observed are not adversely affected by the presence of T cells, B cells or NK cells." (PMID 36411318, 2022). "Thus, inhibiting the CD47-SIRPα anti-phagocytic axis may be a promising strategy to enhance tumor phagocytosis and activate the adaptive immune system." (PMID 35967394, 2022). "Additionally, newer anti-CD47 agents have been developed with inert Fc regions (evorpacept) to further avoid this effector function, though as a result these therapies become reliant on combination therapies involving a tumor-opsonizing antibody." (PMID 36031601, 2022). "Indeed, the disruption of CD47-SIRPα signaling was demonstrated to lead to tumor regression through mechanisms such as promoting phagocytic uptake of tumor cells by macrophages and increasing antigen presentation by DCs, thereby stimulating anti-tumor adaptive immune responses." (PMID 35746616, 2022). "Tumor cells could escape from the innate immunity by expressing high-level CD47 on its surface." (PMID 35422796, 2022). "Further, the preservation of CD47-SIRPγ interaction may benefit anti-tumor immunity." (PMID 36439116, 2022). "However, this also risks mediating immune escape by transferring CD47 to tumor cells." (PMID 35418077, 2022). "Moreover, the CD47-expression could competitively bind with SIRPα, prior to tumor cells, leading to enhancing tumor cell phagocytosis by macrophages." (PMID 35292030, 2022). "Current studies have revealed that monoclonal antibodies targeting CD47 and SIRPα show therapeutic effect in preclinical models of many solid tumors and hematological tumors by promoting macrophage phagocytosis on cancer cells and cancer stem cells, as a new way of tumor immunotherapy." (PMID 35246144, 2022). "When a macrophage engages a tumor cell, the decision whether to tolerate or engulf and destroy it is determined by whether or not the macrophage recognizes the tumor cell as “self,” based on its interaction with CD47 and MHCI on tumor cells." (PMID 36223740, 2022). "Thus, the macrophage prophagocytic response to CD47 blockade may be optimized by using a second signal to activate senescent M2 macrophages to an anti-tumor, M1 form." (PMID 36429020, 2022). "However, studies have reported that tumor cells can highly express CD47, and abnormal activation of the CD47/SIRPα axis by tumor cells may inhibit the anti-tumor immune response and upregulate the threshold for macrophage phagocytosis." (PMID 36119033, 2022).
tumor (continued). "However, irradiated tumor cells express CD47 to escape the anti-tumor immune response." (PMID 36018888, 2022). "Therefore, targeting the CD47/SIRPα axis seems to exhibit very promising efficacy for tumor therapy, which may unlock the therapeutic potential of macrophages." (PMID 35410993, 2022). "CD47 is an innate immune checkpoint that interacts with receptor signaling regulatory protein α (SIRPα), thereby inhibiting phagocytosis by macrophages, and inhibition of the CD47/SIRPα signaling pathway may also limit tumor growth." (PMID 36080373, 2022). "However, CD47 expression is also used by tumor cells to evade detection and phagocytosis by antigen-presenting cells, ultimately hampering the activation of the adaptive response and creating an environment that is permissive for tumor growth and spread." (PMID 36171566, 2022). "Furthermore, CD47–SIRPα has proven to release a self-protection signal leading to tumor immune escape, indicating that this pathway may be an effective target for ICB therapy." (PMID 36672784, 2022). "Although negative regulation of immune responses is predominantly mediated by inhibitory CD47-SIRPα signaling in macrophages and DCs, it remains largely unknown how transgenic CD47 on pig or human pluripotent stem cells and upregulated CD47 on tumor cells interact with its receptor and ligands." (PMID 36454036, 2022). "Therefore, insights raise intriguing questions as to whether anti-tumor effects induced by CD47-antibodies occur through Fc-dependent mechanisms?" (PMID 36081498, 2022). "Conversely, when EVs overexpress SIRPα, due to binding to CD47 on the surface of cancer cells, EVs disrupt the interaction of the cancer cell signaling CD47-SIRPα axis, resulting in increased phagocytosis of cancer cells by macrophages, thereby suppressing tumor growth." (PMID 36297672, 2022). "Moreover, blockade of CD47 induced by antiangiogenic therapy inhibited tumour metastasis." (PMID 35694254, 2022). "Since CD47 is expressed by all cells throughout the body, and SIRPα is only expressed on the neuronal cells and myeloid cells, developing novel strategies to against SIRPα holds much more superiority to enhance tumor‐phagocytosis of macrophages and reduce side effects." (PMID 37323705, 2022). "Our findings suggested that THBS2 might promote cancer progression by remodeling the tumor microenvironment, affecting CD47-mediated signaling pathways, activating the pro-tumor functions of a disintegrin and metalloproteinase with thrombospondin motifs, and enhancing MMP-2 expression." (PMID 35701829, 2022). "It will be important to determine whether and how T cells are involved in the therapeutic effect of CD47 blocking in humans, for example, by defining the T‐cell receptor repertoire after treatment and screening for the frequency of tumour reactivity within the T‐cell population." (PMID 35908284, 2022). "However, whether N-glycosylation affects CD47/ SIRPα binding and tumor immune evasion remains unknown." (PMID 36558902, 2022). "Furthermore, CD47-mediated protection against phagocytosis by macrophages prolongs the retention of exosomes in circulation, and enables cancer cells to manipulate their surroundings and support tumor growth." (PMID 34201127, 2021). "Among them, SαV‐C‐NVs are designed to block CD47‐SIPRα pathway to improve the sensitivity of phagocytes, M1‐NVs are used to repolarize M2‐to‐M1 TAMs, and P‐NVs are mainly employed to enhance affinity to post‐surgical tumor bed, as well as circulating tumor cells (CTCs)." (PMID 34693653, 2021). "Furthermore, blocking both CD47 and MHC I produces a synergistic effect and a stronger tumor suppression, which indicate CD47 and MHC I signals may work cooperatively." (PMID 34178692, 2021). "Notably, miR-708 may function as a tumor suppressor by directly targeting the innate checkpoint CD47 in T-ALL." (PMID 34831008, 2021). "Moreover, CD47 leads to cell death in normal and tumor cells via autophagy." (PMID 33936211, 2021).